CD14 (CD14 molecule)
Diseases named in the same sentence as CD14 in open-access papers (continued):
Sharing a sentence is not in itself a finding about the gene and the disease.
Obesity (83 papers, 2009 to 2026). Accumulation of substantial excess body fat. "Above data suggest that the loss or reduced expression of CD14 mitigates HFD-induced obesity by promoting angiogenesis and increasing EE in ATs." (PMID 39645040, 2024). "Numerous studies have established a positive association between CD14 expression and the development of obesity in human ATs." (PMID 39645040, 2024). "The results from this study suggest that hyperglycemia associated with low-grade inflammation due to obesity alters the percentage of cells expressing CD14+CD95+, death by apoptosis, and microbicidal indices." (PMID 36289594, 2022). "Monocytes and macrophages appear to be associated with adiposity in patients with obesity and COVID‐19, with CD14+CXCR6+ cells positively correlated with the elevated BMI and CD68+ cells in the epicardial adipose tissue." (PMID 35837843, 2022). "We conclude from these results that the most pronounced obesity-associated changes in systemic leukocyte composition from ccRCC subjects are reductions in the percentages of circulating classical CD14+CD16neg monocytes and Tregs." (PMID 32469992, 2020). "In adult studies, activated CD14++ monocytes are associated to obesity and its metabolic and cardiovascular complications." (PMID 32528415, 2020). "The strong association between the obesity-related pathological changes, including inflammation, and CD14 molecules has been demonstrated in rodent models of obesity." (PMID 29615659, 2018). "Mice deficient in TLR4 or its co-receptor CD14 are protected against diet-induced obesity and insulin resistance." (PMID 19513118, 2009). "These interesting data indicate that CD14, zonulin, and cytokines are biomarkers that could be investigated in conjunction with presepsin in infection-free individuals with obesity to provide a clearer picture of the complex underlying pathophysiology." (PMID 40149676, 2025). "GO enrichment analysis demonstrated that Cd14−/− epWATs exhibited significant enrichment in proangiogenic functions, particularly those associated with angiogenesis and vascular development, suggesting that loss of CD14 enhanced angiogenesis during obesity development." (PMID 39645040, 2024). "And the loss of CD14 alleviated high-fat diet–induced obesity in mice." (PMID 39645040, 2024). "Notably, both HFD- and Chow-fed Cd14−/− mice exhibited lower body weights compared with their counterparts, suggesting that CD14 deficiency mitigated obesity development and weight gain." (PMID 39645040, 2024). "In our research, we confirmed the positive correlation of CD14 with overweight and obesity in human subjects and observed that the loss of CD14 could alleviate HFD-induced obesity in mice." (PMID 39645040, 2024). "The activation of TLR-4 and its coreceptor CD14 are associated with obesity and insulin resistance in mice and may represent one of the key elements connecting inflammation to increased susceptibility to weight gain and impaired glucose homeostasis." (PMID 35335996, 2022). "As the reduced frequency of peripheral CD14+ cells was positively correlated with hsCRP, we speculated this may reflect an improvement in obesity-associated low-grade inflammation upon weight loss." (PMID 33082492, 2020). "Indeed, CD14 has repeatedly been suggested before to be associated with the prevalence of obesity and insulin resistance." (PMID 28880885, 2017). "Gut microbiota has been shown to be involved in the development of metabolic syndrome and low-grade inflammation associated with obesity via different mechanisms including lipopolysaccarides-Toll-like receptors/CD14 (LPS-TLRs/CD14) complex mostly in animal models." (PMID 25330000, 2014). "Another interesting possibility is that LPS could be the cause of CD14 activation, lipogenesis, obesity-driven inflammation, and insulin resistance." (PMID 23898465, 2013).
Obesity (continued). "Collectively, our findings indicate that CD14 deficiency increased the accumulation of CD14loCD301b+ macrophages in ATs, which may serve as a proangiogenic marker, providing novel insights into the relationship between CD14 and obesity development." (PMID 39645040, 2024). "Furthermore, it has been shown that in obesity, plasma EVs contain high amount of cystatin C and CD14, that have been correlated with high risk for myocardial infarction, vascular disease mortality and subsequent vascular events, in patients with vascular diseases." (PMID 33339409, 2020). "Intestinal permeability markers including plasma zonulin concentration, serum soluble (s) CD14 levels, and lactulose:mannitol ratio were similar in lean and obesity groups." (PMID 40666326, 2025). "CD14-deficient mice exhibit an ideal body composition with reduced body fat and are resistant to high-fat diet (HFD)–induced obesity, insulin resistance, and dyslipidemia, compared to their wild-type (WT) counterparts." (PMID 39645040, 2024). "In the present study, we analyzed the impact of CXCL10 on circulating CD14/CD16 monocyte subsets from 92 patients with obesity and/or OSAS as well as on THP-1 monocytic cells." (PMID 38175171, 2024). "For instance, in obese individuals, CD14 expression is elevated in adipose tissues (ATs) and shows a positive correlation with the development of obesity." (PMID 39645040, 2024). "CD14 as a surrogate measure of gut permeability is said to be elevated among individuals with obesity and those who adhere to a Western-based diet." (PMID 39114118, 2024). "Beyond its role in immune responses, CD14 has been recognized for its broader role in regulating metabolism, insulin resistance, and obesity." (PMID 39645040, 2024). "In subsequent studies, we observed a significant increase in the frequency of CD301+ macrophages in Cd14−/− mice that were protected from obesity and in healthy weight individuals with lower CD14 expression." (PMID 39645040, 2024). "We studied the distribution of the CD14/CD16 monocyte subsets as well as their CX3CR1 expression patterns in whole-blood measurements from 92 patients with obesity and/or OSAS with regard to plasma CXCL10 values and individual clinical parameters." (PMID 38175171, 2024). "Our findings suggest an angiogenic role for Cd14−/− macrophages in epididymal AT, providing novel insight into the complex interplay between CD14 and the development of obesity." (PMID 39645040, 2024). "Whole blood measurements revealed a significant overall redistribution of CD14/CD16 monocyte subsets in patients with obesity." (PMID 36921085, 2023). "Monocyte subsets of 82 patients with obesity were analyzed in whole blood measurements in terms of the CD14/CD16 cell surface expression patterns and different monocytic adhesion molecules using flow cytometry." (PMID 36921085, 2023). "The link between leptin and CD14 has also been supported by others that found leptin induces CD14/TLR4 activation by the JAK2-STAT3 signaling pathway to promote obesity-related osteoarthritis." (PMID 37447395, 2023). "Here, the colostrum of diabetic mothers with obesity showed an increase in the subsets of cells expressing CD14+." (PMID 36289594, 2022). "The resistin treatment reduced the percentage of cells expressing CD14+CD95+ (36.4 ± 9.2) in the colostrum from diabetic mothers with obesity." (PMID 36289594, 2022). "The down modulation was large in septic patients with diabetes for CD14+% (ds = −0.7 to −1.4) and septic individuals with obesity for CD14+% (ds = −0.9)." (PMID 36687421, 2022). "For further analysis, we obtained WAT biopsies from a cohort of patients with obesity and sorted CD14+ ATMs from subcutaneous and visceral fat depots (scATMs, vATMs) for qRT-PCR analysis." (PMID 36042203, 2022). "Here, the increased death by apoptosis in CD14+ cells expressing CD95+ from the colostrum of diabetic mothers with obesity influenced the functional activity of these cells, reducing their microbicidal capacity." (PMID 36289594, 2022).
Obesity (continued). "For example, CD14 exerts significant proinflammatory impacts in the pathogenesis of metabolic diseases, such as obesity and diabetes mellitus." (PMID 34458379, 2021). "Only CD14+CD16neg classical monocytes and Tregs were reduced when obesity was examined as a categorical variable." (PMID 32469992, 2020). "Systemically, we found decreased percentages of CD14+CD16neg classical monocytes and Foxp3+ regulatory T cells in ccRCC subjects with obesity." (PMID 32469992, 2020). "Although CD14++CD16− (classical) monocytes were detectable in children with obesity in prior studies, the link between monocytes and metabolic impairment has not been clear." (PMID 32528415, 2020). "These indicate that SC-LCBs can control obesity through inhibition of LPS-dependent TLR4/CD14 signal and activation of SCFAs-mediated GPRs proteins." (PMID 31374958, 2019). "The data from the current study for LBP/CD14 as an indicator of obesity agreed with previously published results." (PMID 31491976, 2019). "The LPS-dependent TLR4/CD14 pathway is one of the pivotal signals of the development of obesity resulting from intestinal dysbacteriosis." (PMID 31374958, 2019). "In molecular, LPS-mediated TLR4/CD14 pathway has been recognized as the main mechanism linking gut microbiota and obesity." (PMID 31374958, 2019). "The circulating LPS binds with CD14 and mediates an inflammatory response, thus contributing positively to the development of obesity and insulin resistance." (PMID 31891582, 2019). "The current study is the first to directly test the effect of both Tlr4 and Cd14 gene knock-outs on HFD-induced obesity in the same study." (PMID 30353127, 2018). "The development of MSG-induced obesity resulted in sex-dependent alterations in the frequency of CD14+ cells in SVF, and in the level of its expression." (PMID 29615659, 2018). "On the other hand, we showed that the expression of TRL-4 was increased in monocytes from children with obesity, mainly in CD14++CD16- classical monocytes." (PMID 27977792, 2016). "Metabolic endotoxemia triggers insulin resistance, obesity, and diabetes, through LPS, which in combination with CD14 serves as ligand for TLR." (PMID 26090468, 2015). "To determine if obesity induces a shift in the polarization of the ATMs we measured the ratio of the pro- and anti-inflammatory markers relative to CD14." (PMID 24741586, 2014). "Obesity is strongly associated with the expression of TLR4 (77%, MFI (Mean Fluorescence Index) 7.70) and CD14 (86% MFI 1.61) with 66% double positives (p = 0.000)." (PMID 25493077, 2014). "CD14 is expressed primarily by monocytes, which play important roles in obesity, obesity-induced AT inflammation and insulin resistance." (PMID 24498934, 2014). "A series of reports are in favor of a role of LPS, mainly through TLR4 and CD14, in obesity induced NAFLD." (PMID 21042596, 2010). "Additionally, the expression of CD301/CD301b is negatively correlated with CD14 levels and the obesity development, highlighting the regulatory role of CD14lowCD301+ macrophages in obesity progression." (PMID 39645040, 2024). "The role of the monocyte marker CD14 in the regulation of obesity is increasingly recognized." (PMID 39645040, 2024). "Based on this result, it could be speculated that the increased EE observed in Cd14−/− mice may contribute to their resistance to obesity and the maintenance of a lower body weight during the development of obesity induced by HFD-feeding." (PMID 39645040, 2024). "However, the relationship between CD14 and the development of obesity remains only partially understood." (PMID 39645040, 2024). "In human subjects, CD14 level was tested to be positively correlated with overweight and obesity." (PMID 39645040, 2024). "Also, it is known that CD14 is expressed by monocytes and that these play a crucial role in the inflammation promoted by obesity and insulin resistance." (PMID 35846887, 2022).
Obesity (continued). "Among other cellular populations, CD14++ monocytes in adults with obesity are present in a pro-inflammatory state, favoring the onset of obesity-related complications such as hyperglycemia and atherosclerosis; interestingly, this condition seems to already be present in younger patients." (PMID 35682490, 2022). "Cystatin C and CD14 expression was reported to be pronounced in adipose tissue, suggesting a potential contribution of the adipose tissue-derived EVs to the advance of metabolic complications of obesity." (PMID 33339409, 2020). "Since obesity alters the types of immune cells circulating, along with their activation status, more CD14+CD16+ monocytes may be present after infection of an obese host as compared to a healthy weight host." (PMID 32854687, 2020). "In humans, obesity, measured either as fat mass or by the WHO obesity classification, has been shown to be associated with an increase in intermediate (CD14+CD16+) and non-classical (CD14dimCD16+) monocytes." (PMID 31249530, 2019). "Interestingly, a study in patients with manifest arterial disease or CVD risk factors suggests that EV protein levels of cystatin C positively while CD14 negatively correlate with obesity and obesity-induced metabolic complications." (PMID 31277271, 2019). "Obesity was associated with pro-inflammatory activation of CD14+ phagocytes from adipose tissue in female, but not in male rats, which was demonstrated by decreased phagocytosis activity along with increased ROS generation." (PMID 29615659, 2018). "Therefore, in this study the aim was to compare the effects of either Tlr4 or Cd14 gene knock-outs in mice on the same genetic background for diet-induced obesity in response to a HFD." (PMID 30353127, 2018). "The major differences in gut microbial composition of the Tlr4−/− and Cd14−/− mice did not lead to differences in susceptibility to obesity compared to the Wild-Type mice." (PMID 30353127, 2018). "Absence of CD14 in CD14 deficient ob/ob (CD14 −/−) mice has been shown to protect against diet induced obesity and inflammation in mouse models." (PMID 27703805, 2016). "This increase in plasma LPS induced bya high-fat diet suggests metabolic endotoxaemia, which is considered to trigger thedevelopment of obesity, inflammation, insulin resistance, type 2 diabetes andatherosclerosis via activation of the CD14/Toll-like receptor 4 complex by LPS and/or fattyacids." (PMID 26090097, 2015). "Possibly, two different forms of CD14 studied (soluble CD14 versus membrane-bound CD14) may account for differences in observed relations between obesity and CD14." (PMID 24498934, 2014). "Given the capacity of CD14 to initiate the NFAT pathway, this observation calls for an evaluation of the role of the CD14/NFAT signaling pathway in the control of obesity and insulin resistance once induced by LPS in hematopoietic cells and/or in non-hematopoietic cells including adipocytes." (PMID 23898465, 2013). "Moreover, in addition to the functions in innate immunity, a more general role for CD14 in regulating metabolism, insulin resistance, and obesity is emerging." (PMID 23898465, 2013). "Significant correlations between WAT inflammatory markers and body weight was reported when looking across disparate mouse obesity models, and positive correlations were observed between %CD14+ cells in isolated stromal vascular cells from WAT and BMI in normal weight to obese humans." (PMID 22269778, 2012). "Hence TMEM134 downregulation in childhood obesity and adults with cardiovascular risk may reflect obesity-induced CD14++CD16- and CD14++CD16+ monocytosis." (PMID 29203885, 2017). "Unexpectedly, we found a change in the macrophage phenotype by obesity, with a preponderance of anti-inflammatory (M2) markers and a decrement of proinflammatory (M1) markers in ATMs from obese compared with lean subjects after adjusting the total number of macrophages by CD14." (PMID 24741586, 2014).
Obesity (continued). "In obese animals, batosomes are enriched with proteins involved in signal transduction, cell communication, the immune response, inflammation, thermogenesis, and as obesity biomarkers including UCP1, Glut1, MIF, annexin A6, CD14, and ceruloplasmin." (PMID 36142750, 2022). "Although CD14, CLU, CD99, and SAA2 have been reported to be protein markers for insulin resistance, obesity, and inflammation, our data showed that they only had a modest difference in expression level between healthy and pre-diabetic sera." (PMID 33995275, 2021). "Gram-negative bacteria-derived LPS has been defined as the primum movens in the development of obesity and its related metabolic diseases through binding with toll-line receptor 4 (TLR4) and subsequently activating CD14." (PMID 31374958, 2019). "Moreover, this decrease in the CD14+CD16+ monocyte subset is associated with decreased intima-media thickness, suggesting that the intermediate monocyte subset may contribute to accelerated atherosclerosis and increased risk of CVD in diabetes and obesity." (PMID 31249530, 2019). "Consistently, CD14 mutant mice are resistant to LPS‐initiated metabolic features including obesity, diabetes, and liver fat accumulation and inflammation, indicating that metabolic endotoxemia triggers NAFLD in a CD14‐dependent approach." (PMID 30591521, 2019). "In our experiments, an increased number of CD14+ phagocytes, with low level of this marker expression, was revealed in fat pads of male rats with MSG-induced obesity." (PMID 29615659, 2018). "The use of several different knockout mouse strains, both of TLR4 and CD14, and a variety of mouse diets has complicated our understanding of the role of the TLR4 pathway in the development of obesity." (PMID 30353127, 2018). "Ablation of various pattern recognition receptors (PRRs) such as TLR4, CD14, PKR, and NLRP3 protect mice from diet-/obesity-induced inflammation and insulin resistance." (PMID 25666722, 2015). "Therefore, only the obesity-associated pathologies could be corrected by soluble CD14 but not obesity itself." (PMID 23898465, 2013). "Administration of LPS in CD14-knockout mice on a high-fat diet did not lead to the development of obesity, underscoring the importance of LPS-induced inflammation to weight gain." (PMID 38432562, 2024). "This study investigates abundances and alterations of circulating CD14/CD16 monocyte subsets in patients with obesity with and without OSAS and on the background of manifold clinicopathological phenotypes." (PMID 36921085, 2023). "Like the percentage of CD14+ monocytes, diabetes in septic patients without obesity negatively impacted the CD14+CD16–% (ds = −1.1)." (PMID 36687421, 2022). "The frequency of cells expressing CD14+, independent of resistin treatment, was higher in the colostrum from diabetic mothers with obesity (43.8 ± 19.2 and 41.8 ± 19.1 with and without, respectively)." (PMID 36289594, 2022). "The frequency of cells expressing CD14+CD95+ was higher in cells not treated with resistin in the colostrum from diabetic mothers with obesity." (PMID 36289594, 2022). "The frequency of cells expressing CD14+CD95+ (45.8 ± 16.5) was higher in cells not treated with resistin in the colostrum from diabetic mothers with obesity." (PMID 36289594, 2022). "Previous studies on the abundance of circulating CM (CD14+CD16-) in obesity are inconsistent, with reports showing decrease or no change." (PMID 32074122, 2020). "It is known that CD14+/CD16+ cells display an enhanced pro-osteoclastogenic activity thus supporting the key role of this cells in the alteration of bone health in obesity." (PMID 31130968, 2019). "While this study shows that neither Tlr4 and Cd14 have a role in the HFD-induced obesity HFD has the potential to influence obesity development through Tlr4 and Cd14 independent pathways." (PMID 30353127, 2018).